ARHGAP1 (Rho GTPase activating protein 1)
Description:
GTPase activator for the Rho, Rac and Cdc42 proteins, converting them to the putatively inactive GDP-bound state. Cdc42 seems to be the preferred substrate.
Synonyms: CDC42GAP; RHOGAP1; RhoGAP; p50rhoGAP
Tractability: Small molecule: a structure with a bound ligand is known. Antibody: its Gene Ontology location is reachable by antibodies, with medium confidence. PROTAC: ubiquitination databases record sites on it; its protein half-life has been measured.
Gene: Protein-coding gene on chromosome 11 (46,677,075 to 46,700,977, reverse strand). Ensembl gene ENSG00000175220.
Subcellular location: Cytoplasm
Subcellular location (Human Protein Atlas): Cytosol; Primary cilium; Vesicles
Pathways (Reactome):
Signal Transduction: CDC42 GTPase cycle; RAC1 GTPase cycle; RAC2 GTPase cycle; RAC3 GTPase cycle; RHOA GTPase cycle; RHOB GTPase cycle; RHOC GTPase cycle; RHOD GTPase cycle; RHOF GTPase cycle; RHOG GTPase cycle; RHOJ GTPase cycle; RHOQ GTPase cycle; RND2 GTPase cycle
Gene Ontology:
Molecular function: cadherin binding; GTPase activator activity; protein binding; small GTPase binding
Biological process: endosomal transport; negative regulation of endocytic recycling; small GTPase-mediated signal transduction; transferrin transport; regulation of small GTPase mediated signal transduction; Rho protein signal transduction; signal transduction
Cellular component: cytoplasm; cytosol; endosome membrane; extracellular exosome; perinuclear region of cytoplasm; sorting endosome; cell leading edge; membrane; plasma membrane; ruffle
Genetic constraint (gnomAD): Loss-of-function variants: 23 observed, 54.22 expected, observed/expected ratio (o/e) 0.42, 90% interval 0.3 to 0.6. The upper end of that interval is the gene's LOEUF score, 0.6, which puts it in group 2 of 6, group 1 being the genes least tolerant of losing a copy. Missense variants: 480 observed, 582.92 expected, observed/expected ratio (o/e) 0.82, 90% interval 0.76 to 0.89. Synonymous variants: 210 observed, 235.56 expected, observed/expected ratio (o/e) 0.89, 90% interval 0.8 to 1.
Homologues: Orthologues: chimpanzee ARHGAP1 (99% identical), macaque ARHGAP1 (99% identical), mouse Arhgap1 (97% identical), pig ARHGAP1 (96% identical), dog ARHGAP1 (96% identical), guinea pig ARHGAP1 (95% identical), rabbit ARHGAP1 (95% identical), rat Arhgap1 (95% identical), tropical clawed frog arhgap1 (74% identical), zebrafish arhgap1 (62% identical). Paralogues in human: ARHGAP8 (50% identical).
Diseases named in the same sentence as ARHGAP1 in open-access papers:
ARHGAP1 is named in the same sentence as 52 diseases in open-access papers, as found by Europe PMC text mining. Sharing a sentence is not in itself a finding about the gene and the disease. The quoted sentences say what the papers report.
breast cancer (20 papers, 2009 to 2026). A primary or metastatic malignant neoplasm involving the breast. "For instance, miR-34b-5p expression was alleviated and inhibited cell growth and migration by targeting ARHGAP1 in breast cancer." (PMID 38581057, 2024). "Breast cancer cells also secrete exosomes loaded with miR-940, which enhance the osteogenic differentiation potential of mesenchymal stem cells (MSCs) by suppressing the expression of Rho GTPase-activating protein 1 (ARHGAP1), thereby inhibiting the activation of the RhoA/ROCK signaling pathway." (PMID 40564894, 2025). "However, in breast cancer (BC), ARHGAP1 is a carcinogenic factor, and its expression level in BC samples is higher than that in normal tissues, its overexpression can promote the proliferation and invasion of BC cells while inhibiting its expression can significantly inhibit the growth of tumors." (PMID 38041020, 2023). "Label-free quantitative proteomic analysis of the proteome isolated from the MCF-7 breast cancer cell line, treated with 1 μM of doxorubicin, identified RAC1, CDC42, and RHOA GTPases that were inactivated by the ARHGAP1 protein." (PMID 37511111, 2023).
Ewing sarcoma (4 papers, 2019 to 2023). A small round cell tumor that lacks morphologic, immunohistochemical, and electron microscopic evidence of neuroectodermal differentiation. "Similarly, miR-130b downregulates ARHGAP1 to drive the development of Ewing sarcoma, whereas overexpression of ARHGAP1 reduced the proliferation and migration of human cervical carcinoma cells." (PMID 31533369, 2019).
lung adenocarcinoma (4 papers, 2019 to 2023). A carcinoma that arises from the lung and is characterized by the presence of malignant glandular epithelial cells. "ARHGAP1 is also a direct target of miR-34a and downregulation of ARHGAP1 alone was sufficient to inhibit human lung adenocarcinoma invasion." (PMID 31836741, 2019).
osteosarcoma (3 papers, 2019 to 2023). A usually aggressive malignant bone-forming mesenchymal neoplasm, predominantly affecting adolescents and young adults. "We propose that the miR-509-3p/AXL and miR-509-3p/ARHGAP1 axes have the potential to uncover new druggable targets for the treatment of drug resistant metastatic osteosarcoma." (PMID 31836741, 2019). "However, the role of ARHGAP1 in osteosarcoma has not been reported, which can be further studied in the future." (PMID 38041020, 2023).
depression (2 papers, 2020 to 2025). "ARHGAP1 is an epigenetic-tagged gene in both anorexia nervosa and depression, and this mechanism has been validated by EWAS studies in depression." (PMID 39905509, 2025). "Based on the fact that genetic factors substantially contribute to the observed comorbidity between anorexia nervosa and major depression, we have compelling reasons to believe that epigenetic factors play a pivotal role in the process where the ARHGAP1 gene influences anorexia." (PMID 39905509, 2025). "For the anorexia nervosa and depression pair, despite the limited number of significant genes in both disorders, MAAT identified two genes, ARHGAP1 and PES1, that exert a significant impact on these two diseases." (PMID 39905509, 2025).
anorexia nervosa (1 paper, 2025). A disorder most often seen in adolescent females characterized by a refusal to maintain a minimally normal body weight, an intense fear of gaining weight, a disturbance in body image, and, in postmenarcheal females, the development of amenorrhea. "The pivotal role of ARHGAP1 in anorexia nervosa has been firmly established." (PMID 39905509, 2025).
migraine (1 paper, 2023). "Additionally, we note that many significant genes (e.g., AMBRA1, ATG13, ARHGAP1, CKAP5, LRP4, and DDB2) have been associated with migraine, headache, and proinsulin." (PMID 36808568, 2023).
cancer (42 papers, 2009 to 2025). A tumor composed of atypical neoplastic, often pleomorphic cells that invade other tissues. "Similarly, cancer-secreted EVPs containing miR-940 are internalized by osteoblasts, targeting Rho GTPase activating protein 1 (ARHGAP1) and reticulophagy regulator family member 2 (FAM134A)." (PMID 38707985, 2023). "But it was reported that cancer cells could secrete hsa-miR-940 to the bone microenvironment and induce an osteogenic phenotype by targeting ARHGAP1 and FAM134A." (PMID 34079579, 2021). "In a previous study, we verified that exosomal miR‐141‐3p derived from MDA PCa 2b cells promotes osteoblast activity and osteoblastic bone metastasis, and another study demonstrated that cancer‐derived hsa‐miR‐940 induces osteogenesis by targeting ARHGAP1 and FAM134A." (PMID 33489015, 2021). "Thus, the level of ARHGAP1 appears critical for the aggressiveness of cancer cells, rendering a dysregulation of its cytosolic level by mislocalization to peroxisomes a prime candidate for further studies." (PMID 31533369, 2019). "Interestingly, ARHGAP1 has been found as a target of the micro-RNA hs-miR-940, which is spread via exosomes from diverse cancer cells and promotes osteogenic differentiation of human mesenchymal stem cells." (PMID 31533369, 2019). "Combination with ten cancer types in pan-cancer, four mRNAs (PBX3, KLF6, ARHGAP1, ST3GAL2) were selected out." (PMID 32519740, 2020). "Particularly, cancer exosomal miR-940 was able to induce the osteogenic differentiation of mesenchymal stem cells, by targeting ARHGAP1 (Rho GTPase Activating Protein 1) and FAM134A (Family With Sequence Similarity 134 Member A)." (PMID 29642618, 2018). "Similarly, emerging evidence implicates dysregulation and decreased expression of RhoGAPs (ARHGAP1), B4GAT1, and FGA in various malignancies, including cancer." (PMID 39819313, 2025).
tumor (35 papers, 2009 to 2025). "Although the role of ARHGAP1 in CRC has remained obscure, alteration of ARHGAP1 might contribute to tumor aggression." (PMID 26543234, 2015).
ARHGAP1 also shares sentences with these, for which no sentence is quoted: hepatocellular carcinoma (9 papers); colorectal cancer (3); liver cancer (3); lung carcinoma (3); melanoma (3); osteoporosis (3); prostate carcinoma (3); arterial hypertension (2); cervical carcinoma (2); glioblastoma (2); infection (2); Alzheimer disease (1); Anorexia (1); Anxiety (1); atherosclerosis (1); autism spectrum disorder (1); bladder cancer (1); bone disorder (1); breast tumor (1); cardiovascular disorder (1); COVID-19 (1); cutaneous melanoma (1); cystic fibrosis (1); dementia (1); diabetes (1); diabetic kidney disease (1); endometrial cancer (1); epilepsy (1); gastric cancer (1); glioma (1).
A further 13 diseases each share a sentence with ARHGAP1 in 1 paper.